MMP9 (matrix metallopeptidase 9)
Diseases named in the same sentence as MMP9 in open-access papers (continued):
Sharing a sentence is not in itself a finding about the gene and the disease.
cervical carcinoma (continued). "Increased MMPs expression, including MMP-2, MMP-9 and MT1-MMP, has been observed during cervical carcinoma progression." (PMID 22438955, 2012). "In cervical cancer, we found a strong upregulation of VEGF-C and MMP-9 mRNA, with a highly significant co-expression between MMP-9 and VEGF189." (PMID 12189553, 2002). "The lymphangiogenic factor VEGF-C is strongly co-expressed with MMP-9, VEGF189 and b-FGF in cervical cancer." (PMID 12189553, 2002). "Nonetheless, our findings have revealed a clear relationship between increased MMP-9 mRNA and cervical cancer, increasing the probability that MMP-9 plays a key role in the progression of early-stage cervical cancer." (PMID 12189553, 2002). "In contrast to normal cervical tissue, we found a highly significant co-expression (P<0.0001) between MMP-9 and VEGF189 in cervical cancer." (PMID 12189553, 2002). "To determine whether cervical cancer cells conditioned media (SiHa and HeLa) can promote differentiation towards an MSC-CAF phenotype we evaluated vimentin, S100A4, αSMA, FAP, and MMP9 expression by immunofluorescence." (PMID 38606999, 2024). "Similarly, in cervical cancer cell lines, PTX3 knockdown resulted in reduced expression of key molecules involved in tumor cell migration and invasion, including MMP2, MMP9, and urokinase." (PMID 39594709, 2024). "Our integrated analysis of databases revealed that MMP-9, EGFR, AKT, and caspase-3 may be the drug targets of naringenin in cervical cancer." (PMID 38253629, 2024). "Likewise, genistein treatment inhibited MMP-9 expression and increased the expression of TIMP-1 in HeLa cervical carcinoma cells." (PMID 39335164, 2024). "Additionally, studies on SiHa and HeLa cervical cancer cells have shown that ALA and n-3 fatty acids regulate the growth of cervical cancer cells by reducing cell migration with a concomitant reduction in the expression of MMP-2, MMP-9, and VEGF." (PMID 37761033, 2023). "In our study, MMP-9 was not expressed in most of the postmenopausal atrophic endometrium compared to the premenopausal proliferative endometrium." (PMID 36945954, 2023). "Previous studies showed that MMP9 alone did not significantly affect the survival rate of cervical cancer; however, in the present study, when TME macrophages decreased, there was an impact on OS, and the OS with high ERBB3 was significantly reduced." (PMID 36911370, 2023). "Further, we verified the promotional effect of KNTC1 on cervical cancer through in-vivo and in-vitro experiments and speculated that KNTC1 might mediate tumor invasion via MMP9 and MMP2." (PMID 35389773, 2022). "Similarly, the down-regulation of FABP5 in cervical cancer inhibits the in vivo and in vitro expression of MMP-2 and MMP-9." (PMID 35445019, 2022). "Primary cervical cancer with an EMT phenotype showed increased tumour progression, migration, invasion and deformation in epithelial integrity, while activation of the Akt pathway is required for MMP9‐induced EMT." (PMID 35137520, 2022). "Furthermore, the two oncogenes upregulate matrix metalloproteinase 2 (MMP-2) and matrix metalloproteinase 9 (MMP-9) and induce epithelial-mesenchymal transition (EMT) transcription factors in cervical cancer and head and neck squamous cell carcinoma (HNSCC)." (PMID 35421154, 2022). "This study demonstrated that HK2 could activate Akt1 in cervical cancer cells, subsequently enhancing cell motility and tumor metastasis by inducing FN1, MMP2 and MMP9 expression." (PMID 34758823, 2021). "In addition, baicalin can also inhibit the migration and invasion of cervical cancer HeLa cells by downregulating the expression levels of MMP2 and MMP9 through the p38-MAPK pathway and has a concentration-dependent effect to a certain extent." (PMID 34421596, 2021). "In conclusion, this study demonstrated that HK2 could activate Akt1 (p-Akt1) in cervical cancer cells, subsequently enhancing cell motility and tumor metastasis by inducing FN1, MMP2, and MMP9 expression." (PMID 34758823, 2021).
cervical carcinoma (continued). "In cervical cancer, HOXA11-AS silencing was shown to decrease the expression of matrix metalloproteinase-2 (MMP-2), MMP-9, and vascular endothelial growth factor and increase the number of CD133+CD44+ cells, indicating an increase in the cancer stem cell population." (PMID 31757938, 2019). "In cervical cancer, dysregulation of MMP-2 and MMP-9 has been widely reported." (PMID 30484490, 2018). "Down-regulation of FZD7 in cervical cancer cells could inhibit cell invasion and migration by inhibiting the expression level and activities of MMP2 and MMP9, as well as inhibiting the expression of phosphorylated JNK and c-jun." (PMID 29029485, 2017). "However, the expression of PTX3 promotes cervical cancer metastasis and EGF-induced HNSCC metastasis via the up-regulation of MMP-2 and MMP-9." (PMID 28489600, 2017). "Therefore, we focused on MMP-2 and MMP-9 when investigating the molecular mechanism by which PLOD2 reduces the migration and invasion of cervical cancer cells in hypoxic conditions." (PMID 28507454, 2017). "Furthermore, knockdown of PTX3 significantly decreased the potential of migration and invasion of cervical cancer cells by inhibiting matrix metalloproteidase-2 (MMP-2), MMP-9, and urokinase plasminogen activator (uPA)." (PMID 27377307, 2016). "Taken together, our findings suggest that HOTAIR may promote cervical cancer cell migration and invasion through the upregulation of VEGF and MMP-9 expression." (PMID 25405331, 2015). "IL-17A could promote the migration and invasion of cervical cancer cell via up-regulating MMP2 and MMP9 expression, and down-regulating TIMP-1 and TIMP-2 expression via p38/NF-κB signal pathway." (PMID 25250801, 2014). "Zta upregulates MMP9 in a cervical carcinoma cell line but the biologic effects of Zta-induced MMP9 on this cell line have not been tested previously." (PMID 23409137, 2013). "Interestingly, MMP9 and MMP2 up-regulation in cervical cancer was previously reported and the combined overexpression of MMP9, MMP11 and TIMP1 has been associated with the invasive features of some cancers." (PMID 15989693, 2005). "In our study, both VEGF189 and VEGF-C appear to be strongly co-expressed with MMP-9 in cervical cancer but not in normal cervical tissue." (PMID 12189553, 2002). "This is the first report showing that bergenin firstly reduced MMP-9 levels and secondly bergenin binds MMP-9 more efficiently as compared to galectin-3, suggesting a cumulative effect of bergenin on Galectin 3 and MMP 9 leads to reduced migratory characteristics in cervical carcinoma cells." (PMID 38961106, 2024). "However, the present study revealed that the expression of MMP9 was not a significant predictor of OS in patients with cervical cancer." (PMID 36911370, 2023). "Taken together, the results obtained have suggested that the MALAT-ALKBH5 signaling axis may be activated in HPV-positive cervical cancer cells, which could contribute to cell proliferation and metastasis through the regulation of key genes, such as MMP2 or MMP9." (PMID 37639643, 2023). "After silencing DPP8 in human cervical cancer cell lines, G1 phase arrest increased Bax expression, decreased BCL2 expression, inhibited cell proliferation, promoted cell apoptosis, and inhibited the expression of MMP2 and MMP9, reducing cell migration and invasion." (PMID 36172198, 2022). "Several studies have demonstrated elevated levels of MMP-9 in the tumor tissue and plasma of patients with CRC, and MMP-9 level has been suggested as a biological predictor of prognosis in CRC, as well as in other types of cancer such as breast and cervical cancer." (PMID 29520667, 2018). "Finally, we analyzed RECK and MMP-9 expression levels in clinical samples from patients diagnosed with cervical cancer and observed (I) downregulated RECK protein expression and (II) upregulated MMP-9 protein expression in cervical cancer when compared to CIN 1 or normal cervical tissue 27,31." (PMID 30208169, 2018).
cervical carcinoma (continued). "Moreover, HOTAIR may promote cervical cancer progression by inducing cell migration and invasion through the upregulation of VEGF, MMP-9 and expression of EMT-related genes." (PMID 25405331, 2015). "In addition, MMP-9 is strongly co-expressed with VEGF189 in cervical cancer but not in normal cervical tissue." (PMID 12189553, 2002). "However, in cervical cancer, VEGF-C is strongly co-expressed with MMP-9, VEGF189 and b-FGF." (PMID 12189553, 2002). "Interestingly however, the Oct4B isoform has been identified to regulate both MMP2 and MMP9 expression in cervical cancer, suggesting the lack of MMP9 suppression may be due to the fact that Oct4B expression was not specifically suppressed in the current study." (PMID 27390927, 2016). "We have previously shown that expression of MMP-9 and MT1-MMP is higher in HPV positive than in HPV negative cervical cancer derived cell lines." (PMID 22438955, 2012). "SCs displayed increased expression of MMP-2, MMP-9, and MMP-12 at the protein level after co-cultivation with cervical cancer cells, whereas no change in the expression of these MMPs was detected in HeLa and ME-180 cells, differing from previous report about pancreatic adenocarcinoma cells." (PMID 32064233, 2020). "The differential effect between cervical cancer cell lines and esophageal squamous cell lines could be a reflection of the cellular context of the gene environment, highlighting that MMP2 and MMP9 are downregulated by several miRNAs, independent of UTR binding sites." (PMID 30696040, 2019).
aneurysm (148 papers, 2004 to 2025). Bulging or ballooning in an area of an artery secondary to arterial wall weakening. "CCR2+ macrophage tissue infiltration was associated with overall aneurysm deterioration, such as severe elastin degradation and increased MMP9 24 and MMP2 25 activity when compared to controls." (PMID 40365294, 2025). "MMP-9 is a matrix peptidase derived from the zinc component that is involved in the extracellular matrix proteolysis and is directly linked with aneurysm development and passing away in both the infrarenal and thoracic aortas." (PMID 41155271, 2025). "Elevated levels of MMPs, particularly MMP-9, have been associated with the weakening of the arterial wall, contributing to aneurysm development." (PMID 39410571, 2024). "DM can also promote the inflammation process and increase the levels of MMP9 in the arterial walls, all of which can cause aneurysm wall degradation and rupture." (PMID 38090273, 2023). "As previously reported, MMPs, in particular MMP-9, have been implicated in aneurysm growth through structural changes in the aortic wall and ECM remodeling." (PMID 35054350, 2022). "The MMP-9-positive cells were abundant in tunica adventitia of the aneurysm, supposedly associated with inflammatory cells of this layer, but MMP-9-positive cells were also present in the tunica media and assumed to be in VSMCs (arrows)." (PMID 36186984, 2022). "In ICH, although MMP-9 has shown some association with the development of aneurysms and arteriovenous malformations and with the increase risk of ICH, as a marker of unstable vasculature, in spontaneous ICH these findings have been few." (PMID 34685473, 2021). "Previous studies showed that high plasma MMP-9 levels are associated with increased AA and AD formation and especially aneurysm rupture." (PMID 34769592, 2021). "At the same time, MMP-2, neutrophil gelatinase-associated lipocalin (NGAL) and MMP-9 are expressed in the aneurysm wall and are involved in aneurysm development and expansion." (PMID 34439968, 2021). "The analysis using BM chimeric mice revealed that aneurysm formation and MMP-9 expression were enhanced by CCL3 deficiency restricted to BM-derived cells." (PMID 33239616, 2020). "Specifically MMP-2 and MMP-9 have been implicated in the pathogenesis of aneurysm due to their capability to degrade elastin and increased expression levels in the aneurysm tissue and the plasma of patients." (PMID 22187650, 2012). "Furthermore, genetic factors such as variations in MMP-9 gene polymorphisms have been associated with aneurysm formation in KD." (PMID 39410571, 2024). "Among them, MMP-9 has been recently reported to have a consistently higher level in aneurysm SAH patients, which may cause cerebral vasospasm, DCI, and neuronal death by promoting neuroinflammation." (PMID 36505409, 2022). "On the other hand, the role of chymase-activated MMP-9 is deeply involved in inflammatory cell accumulation, which may be particularly relevant to inflammation-associated cardiovascular diseases such as aneurysm." (PMID 36289761, 2022). "In addition to MMP-9, various other neutrophil-derived MMPs are elevated and support the pathogenic process in aneurysm development." (PMID 34572424, 2021). "End-stage experimental aneurysm is associated with a shift towards cells that express high level of MMP-9, which may trigger substantial collateral tissue damage when released, further driving the aneurysmal phenotype." (PMID 31320700, 2019). "In hypertensive patients elevated plasma levels of matrix metalloproteinase-9 (MMP-9) have been reported, which may be the cause of increased proteolytic activity in the aortic wall and thus lead to aneurysm formation." (PMID 23326585, 2013). "Specifically, MMP-2 and MMP-9 are prominent in aneurysms; MMP-9 is elevated in both TAAs and AAAs, as well as in Marfan syndrome, whereas MMP-2 is predominantly increased in AAAs." (PMID 41463310, 2025).
aneurysm (continued). "Our group recently demonstrated that IFN‐γ stimulates the expression and activities of MMP‐2 and MMP‐9 in vivo and in vitro, leading to aneurysm formation." (PMID 40932621, 2025). "Elevated MMP activity, especially MMP-2 and MMP-9, is positively correlated with aneurysm diameter and severity, highlighting the importance of protease-mediated vascular remodeling." (PMID 40869102, 2025). "They found a significant increase in expression of MMP-1 (a collagenase) and MMP-9 (a gelatinase) in aneurysm and dissection patients compared with controls." (PMID 39830801, 2025). "Previous work demonstrates that MMP2 plays a central role in the formation and early expansion of AAAs, while MMP9 is more related to late AAA expansion and risk of aneurysm rupture." (PMID 38228786, 2024). "Persistent release in the bloodstream of MMP-9 has further been related to aortic degeneration, increase in aneurysm size, and its expansion." (PMID 39408865, 2024). "Increased levels of MMP-9 have been identified in the vessel wall of aortic aneurysms and are correlated with aneurysm diameter, supporting the argument that MMP-9 has a key role in the development of aneurysms resulting from decreased serum AAT levels." (PMID 38283099, 2024). "Activation of MMP2 and MMP9 and the arising disruption or loss of ECM significantly affect the integrity of the aortic wall and contribute to aneurysm formation." (PMID 39011492, 2024). "Following endovascular repair, MMP-9 can be used as a circulating marker to predict the development of aneurysms and endoleakage." (PMID 37007957, 2023). "The reduction in aneurysm size correlated with reduced expression of matrix metalloproteinases Mmp2 and Mmp9." (PMID 37686377, 2023). "Conversely, MMP-9 is predominantly expressed by macrophages, and its activity as assessed by zymography, is increased in ruptured aneurysms when matched to similar sized intact AAAs." (PMID 37799778, 2023). "Treatment with 17 β-estradiol did, however, result in reduced levels of two well-established molecular markers of aneurysm pathology, matrix metalloproteinase-2 (Mmp2) and matrix metalloproteinase-9 (Mmp9), in male Marfan mice." (PMID 37686377, 2023). "MMP-2 and MMP-9 degrade elastin and collagen, and their absence in rats inhibits the development of aneurysms." (PMID 37007957, 2023). "Further investigation into the role of FMRP in regulating MMP-9 translation in vasculature and cardiac valves is warranted, especially given the difference in natural history of aortic dilatation and aneurysms between Marfan and FXS." (PMID 36140728, 2022). "As in the elastase induced aneurysms, the mean number of MMP-9-positive cells/mm2 in aneurysmal tissue was unaltered after XPro1595 treatment compared to vehicle-controls." (PMID 36186984, 2022). "In contrast, the MMP‐9, a pro‐inflammatory extracellular lysis enzyme mainly produced by macrophages, was reduced in the BBAs compared with that in the saccular aneurysms (p < 0.05)." (PMID 34970805, 2022). "Nevertheless, MMP-9 has been documented as a reliable plasmatic marker of the final stages of aneurysm development processes in subjects with chronic thoracic aortic disease." (PMID 35563383, 2022). "For instance, imatinib can prevent aneurysm progression by inhibiting the expression and activation of matrix metallopeptidase 9 in experimental AAA models." (PMID 36588574, 2022). "The results of this study also confirmed that the expression and activity of MMP2 and MMP9 were significantly increased in the three groups of aneurysms." (PMID 35282381, 2022). "MMP-2 is the primary metalloproteinase in minor aneurysms, whereas MMP-9 is involved in late aneurysm development." (PMID 35745168, 2022). "Of interest, increased expression of multiple genes in Tsc2 deficient macrophages including Mmp9, Fosl1, Fos and TSP-1 were involved as the downstream targets of CREB and associated with aneurysms formation." (PMID 36400753, 2022).